ARG1 (arginase 1)
Diseases named in the same sentence as ARG1 in open-access papers (continued):
Sharing a sentence is not in itself a finding about the gene and the disease.
infection (continued). "Expression of iNOS and Arg1 was consistently detected during the acute and chronic phases of infection with low and high doses of the virulent laboratory strain H37Rv, and also using the hypervirulent clinical isolate HN878." (PMID 25790379, 2015). "For that, we injected intravenously C57BL/6 mice with stationary promastigotes of each L. infantum strain and analyzed the liver expression of Nos2 and Arg1 as well as of Tnf, Ifng, Il-12p40 and Il-10 genes, 15 and 60 days after infection." (PMID 26684322, 2015). "We also noted changes in the expression of transforming growth factor-1 (tgfβ1) in the SN starting at 7 days post-infection (dpi) that was sustained through 21 dpi, coupled with increases in arginase-1 (arg1) and csf1, M2 markers for microglia." (PMID 25861024, 2015). "In contrast, our immunohistochemistry results show that LysMcreIL-4Rα-/lox mice had comparable levels of iNOS and Arg1 when compared to wild-type mice during acute/chronic phase of infection with low-dose Mtb H37Rv (100 CFU/mouse)." (PMID 25790379, 2015). "Two studies, including our own work, showed that antibody-activated Arg1 expressing MΦ limit the motility of tissue-dwelling helminth larvae, thereby preventing tissue damage during early challenge infection with Hpb or N. brasiliensis, respectively." (PMID 25806513, 2015). "Arg1 protein expression was increased in macrophages isolated from the spleens of hamsters with VL starting at 14 days post-infection." (PMID 24967908, 2014). "We found that parasitized macrophages were not deactivated but showed a M2 ("alternatively activated") phenotype where the expression of host arginase 1 (arg1) dominated at the site of infection." (PMID 25424735, 2014). "Compared with this, arg1 expression was significantly elevated in lungs from infected IL-13tg mice 21, 42 and 63 days after infection." (PMID 24979482, 2014). "Inhibition of FGFR-1 and IGF-1R decreased arg1 expression and restricted L. donovani replication in both in vitro and ex vivo models of infection." (PMID 24967908, 2014). "In contrast, Arg-1, an M2-specific enzyme in macrophages, showed a slight decrease at week 3 after infection, followed by a marked upregulation at week 8 after infection." (PMID 24666892, 2014). "Treatment of L. donovani-infected hamster BMDMs over 24 hrs of infection with an inhibitor of FGFR-1 resulted in a significant dose-dependent reduction of arg1 mRNA expression and parasite burden without affecting cell viability." (PMID 24967908, 2014). "Another study, however, found that Arg1-expressing immunoregulatory antigen presenting cells induced during C13 infection suppressed T cell responses." (PMID 25250029, 2014). "Recently, we have demonstrated that L-arginine supplementation improved mucosal recovery following C. parvum infection plus undernutrition and that ileal arginase 1 was a marker of infection severity." (PMID 24586873, 2014). "The susceptibility of these populations of RAMs from different inbred lines of rats, as measured by infection levels, was completely correlated with arginase-1 activity and inversely correlated with NO production." (PMID 23691079, 2013). "MKP-2−/− mice did not, however, demonstrate defective type-1 responses compared with MKP-2+/+ mice following infection although they did display significantly reduced serum nitrite levels and enhanced tissue arginase-1 expression." (PMID 23966857, 2013). "BMMφs infected with TgCtwh3 shared the features of high Arg-1 and Ym1 expression, which were similar to those with RH strain, while TgCtwh6 infection induced strong iNOS expression." (PMID 24499603, 2013). "Depletion of L-arginine, as a result of the generalised elevated Arginase-1 levels in MKP-2−/− mice would explain the general T cell hypo-responsiveness observed in these mice following infection with L. major." (PMID 23437409, 2013).
infection (continued). "Western blot analysis demonstrated that BMMΦ from obese mice produced much more Thbs1 and Arg1 proteins after 4 h infection compared with BMMΦ from lean mice." (PMID 23922979, 2013). "Increased expression of arginase-1 following macrophage infection with T. gondii was also reflected in up-regulated enzyme activity at 24 hours post-infection in both MKP-2−/− (p<0.05) and MKP-2+/+ macrophages." (PMID 23966857, 2013). "T. gondii tachyzoite infection was found to enhance macrophage arginase-1 expression although this was consistently higher in MKP-2−/− than in MKP-2+/+ macrophages up to 24 hours post-infection." (PMID 23966857, 2013). "In fact, we observed a consistent, modest increase in intracellular bacteria 48 hours after infection among Arg1-/- infected cells compared to controls." (PMID 24324751, 2013). "The critical importance of the parasite-induced STAT6-arg1 pathway in infected cells was demonstrated by finding enhanced control of infection following either STAT6 or arg1 knockdown." (PMID 22275864, 2012). "Arginase 1 (Arg 1) has been induced in alternatively activated macrophages (AAMs) and function in part to suppress NO production in intracellular infection." (PMID 22558235, 2012). "We next showed that like hamster macrophages, in vitro infection of BHK fibroblasts resulted in parasite-induced arg1 mRNA expression." (PMID 22275864, 2012). "After 8 days of infection, the levels of iNOS expression rose in mouse skin infected by the ΔaaaA mutant compared to the WT and complemented mutant whilst expression of Arg1 tended towards a fall in the ΔaaaA mutant." (PMID 22927813, 2012). "Infection of these cells with the mycobacterial strains promoted expression of M2 markers, further increasing expression of the Arg-1 and suppressing inhibition of the MR expression induced by the H37Rv and B2 strains." (PMID 22863292, 2012). "To dissect the role of STAT6 in L. donovani-induced arg1 expression we used the in vitro infection model of the BHK hamster fibroblast cell line." (PMID 22275864, 2012). "We first demonstrated that, like hamster macrophages, hamster primary splenic fibroblasts expressed arg1 in response to in vitro infection with L. donovani." (PMID 22275864, 2012). "Paralleling the STAT6 phosphorylation results, wild-type and complemented parasites, but not ΔROP16 tachyzoites, induced arginase-1 synthesis, a response detectable by immunoblotting for arginase-1 protein within 6 hr of infection." (PMID 21931552, 2011). "Both Arg1flox/flox;Tie 2-cre and Arg1+/+;Tie 2-cre mice had parasite worm burdens at D35 post-infection consistent with chronic infection." (PMID 21585399, 2011). "Compared to >50% of the cells expressing Arg1 at 48 after infection, only 2.5% of the cells were found to be NOS2+ by intracellular staining techniques." (PMID 21246055, 2011). "As early as 6 hours after infection, the expression of Arg1 and Fizz1 was detected in the infected lungs when compared to uninfected controls but no induction of NOS2 was noticed." (PMID 21246055, 2011). "The results are plotted as the ratio of percent host infection in recipients of infected Arg1−/− MØ relative to recipients of Arg1+/+ MØ." (PMID 21931552, 2011). "More evidence for an in vivo role of arginase-1 during infection comes from recent findings with Leishmania major and Schistosoma mansoni." (PMID 21931552, 2011). "We reasoned that if ROP16-mediated arginase-1 induction limited in vivo growth, emergence of ΔROP16 parasites and subsequent infection of CD45.2 host cells would occur more rapidly than during RH infection." (PMID 21931552, 2011). "In this respect, protein (western blot) and mRNA (real-time RT-PCR) levels of arginase-1 and arginase-2 were analyzed in diencephalic brain structures during the time course of the infection." (PMID 21408057, 2011).
infection (continued). "It is possible that functional cooperation between IL-4Rα/STAT6 and additional pathways promotes maximal Arg1 expression in alveolar macrophages after infection with A. fumigatus." (PMID 21246055, 2011). "For example, a recent study showed that Arg1, the key enzyme expressed by AAMs, can be detrimental during infections by intracellular pathogens such as T. gondii and M. bovis." (PMID 21246055, 2011). "In this study, we observed that rapidly after infection by A. fumigatus, alveolar macrophages predominantly express Arginase 1 (Arg1), a key marker of alternatively activated macrophages (AAMs)." (PMID 21246055, 2011). "In those studies, arginase-1 induction in myeloid cells promoted infection by localized depletion of arginine, in turn leading to suppressed T cell responses." (PMID 21931552, 2011). "Straightforward infection of arginase-1 knockout or MØ-specific arginase-1 knockout mice was problematic because of issues of lethality for arginase-1 knockout mice." (PMID 21931552, 2011). "Arginase-1 production by MΦ is also important in wound healing and is a feature of tissue remodeling after repeated infection of the skin by schistosome cercariae (PC Cook & AP Mountford; manuscript in preparation)." (PMID 19829705, 2009). "Recently, it has been shown that cytokine-dependent, STAT 6-dependent pathways as well as TLR-dependent, STAT-6 independent pathways can induce arginase-1 in macrophages depending on the type of infection." (PMID 19696894, 2009). "Here, however, we show that macrophage-specific Arg1 functions as an inhibitor of inflammation and fibrosis following infection with the Th2-inducing pathogen Schistosoma mansoni." (PMID 19360123, 2009). "Similarly, the HIF-2α-specific target gene Arg1 is also highly expressed in monocyte-derived macrophages and Arg1 is significantly upregulated during infection." (PMID 40191198, 2025). "Importantly, during the later phase (7 days post-infection), there was a significant upregulation of M2-/Th2-related markers, including Arg-1, IL-4, and IL-10, in K. pneumoniae_OMVs-immunized mice relative to the PBS group." (PMID 41472051, 2025). "During infection, the majority of ARG1 expressing cells were labeled by tdTomato." (PMID 40568097, 2025). "Along the course of infection, there was a reduction in the expression of M1 markers like Nos2, Cd40,Cd86, Tnfa, Nfkb2, Il6 and a corresponding increase in the expression of the M2 markers such as Arg1, Ccl17, Cd206, IL4ra with an exception of Tgfb." (PMID 39693143, 2024). "(E) In vitro infection of unpolarized (M0) bone-marrow-derived murine macrophages (BMDMs) resulted in a down-regulation of TRM-associated marker Mrc1 and an upregulation of M2-like markers Nos2 and Arg1." (PMID 38767331, 2024). "Furthermore, during the acute infection stage, the genes Arg1, Arg2, Ckb, and Nos2 displayed upregulation and were found to be enriched in the arginine and proline metabolism pathway." (PMID 38229193, 2024). "Infection with S.tm further increased ARG1 expression in F4/80+CD11b+ macrophages." (PMID 37190073, 2023). "Thus, it is tempting to assume that the increase in polyamines in unpolarised BMDM stimulated with IL-4 after infection with S.tm is primarily driven by the metabolisation of L-arginine by IL-4-dependent ARG1." (PMID 37190073, 2023). "Importantly, priming of macrophages with IL-4 (pre-stimulation) increased Arg1 expression compared to BMDM stimulated with IL-4 after establishment of the infection." (PMID 37190073, 2023). "The spleen-specific upregulation of CEACAM1 and ARG1 genes was observed after infection." (PMID 36835242, 2023). "Taken together, these data indicate that the time point when macrophages are stimulated by cytokines in the course of an infection with S.tm accompanied by the modification of ARG1 and iNOS expressions is of utmost importance for controlling an infection with Salmonella." (PMID 37190073, 2023).
infection (continued). "RT‐qPCR experiments showed that Kp52145 infection increased the levels of the M(Kp) markers arg1, il10, nos2, the ISG isg56 and ido in THP‐1 cells in a STAT6‐dependent manner because the STAT6 inhibitor AS1517499 abrogated Klebsiella‐mediated upregulation of these M(Kp) markers." (PMID 36337046, 2022). "We, therefore, quantified SC mRNA levels encoding various pro-inflammatory and disease resolving factors, namely, the monocyte chemoattractant CCL2, TNF, IFNγ, a prominent mediator of MHV virus control, iNOS, IL10 and arginase 1 (Arg1) over the course of infection." (PMID 36333761, 2022). "Some studies suggest that, notably through the synthesis of polyamines, Arg1 might promote tissue repair during infections." (PMID 35154105, 2022). "Even at the chronic stage of infection (42dpi), which is expected to have a M2 macrophages bias, cells from monocyte-derived macrophage subpopulation are Nos2/Arg1 double positive, indicating a mix phenotype that cannot be categorized along the M1/M2 paradigm lines." (PMID 36420267, 2022). "While the function of ARG1 in infections with Leishmania spp." (PMID 34359992, 2021). "Recovery of CD163+ PAMs, together with an increase of Arg-1+ PAMs, was observed at two weeks post-infection which point out that pulmonary macrophages were polarised to M2, but also, an attempt to reconstitute the pulmonary macrophages subpopulations lost during the early stages of the infection." (PMID 33482914, 2021). "Additionally, it was also reported that high Arg-1 expression preceded the increased induction of iNOS at early time points of infection with mycobacteria." (PMID 34925356, 2021). "On the other hand, Arg1 expression was high at baseline and further elevated by day 5 of infection." (PMID 33849979, 2021). "Furthermore, immunohistochemical images revealed that the intense labeling Arg-1 after 11 weeks of infection coincides with areas with vacuolated macrophages filled with parasites." (PMID 34660334, 2021). "Furthermore, critical anti-helminth effector molecules, Arg1, Retnlb and Gob5, and circulating H. polygyrus-specific IgG1 titres were unaltered following 2° infection." (PMID 33846533, 2021). "We therefore investigated whether an ARG1 deletion has an effect on the course of infection with S.tm in vivo." (PMID 34359992, 2021). "Our group also showed that infection of STAT6 deficient mice on the C57BL/6 background was associated with an almost complete abrogation of Arg1 expression by phagocytic cells, but this did not restrict parasite growth." (PMID 34557194, 2021). "However, after 11 weeks of infection, such balance was reversed, with a substantially higher proportion of marking for Arg-1 in the BALB/c paws compared with C57BL/6 mice." (PMID 34660334, 2021). "We also found a higher Arg-1/iNOS ratio in C57BL/6 mice than in BALB/c after 240 h of infection." (PMID 34660334, 2021). "Thus, C57BL/6 mice have a more effective response against L. amazonensis, based on a balance between inflammation and tissue repair, while BALB/c mice have an excessive Arg-1 production at late infection." (PMID 34660334, 2021). "In addition, along with the extension of infection time, the expression of ARG-1 showed a rising trend in multiple myeloid cells, whereas the expression of the CD3ζ chain showed a decreasing trend." (PMID 32029006, 2020). "As infections are resolved, elevated levels of interleukin-4 (IL-4) and IL-13 promote the repolarization of macrophages to an anti-inflammatory alternative or M2 polarization state, which is accompanied by increased expression of arginase-1 (Arg1)." (PMID 32857777, 2020). "While this might suggest that this inhibition was removed or weakened post-Cn infection, the relatively small difference in M2 marker expression (e.g. Arg1) and the re-establishment of a more M0-like state indicated this may not be the case." (PMID 32857777, 2020).
infection (continued). "In the chronic phase, we found that the expression of ARG-1 exhibits a rising trend in multiple peritoneal myeloid cells along with the extension of infection time, except for fluctuations in SSClowCD11b+F4/80+ and CD11b+CD11c+ cells at 12 months post-infection." (PMID 32029006, 2020). "The induction of iNOS in macrophages in vitro, and the expression of Arginase-1 and of IL-10 in vivo, was not altered in MyD88-deficient cells/mice after infection with NMII." (PMID 30800124, 2019). "Arg-1, the canonical marker of M2 macrophages, is supposed to exhibit both anti-inflammatory and anti-fibrotic activity after infection with S. mansoni, and Arg1-expressing macrophages act as critical mediators to downmodulate the immune response in chronic schistosomiasis." (PMID 31888743, 2019). "Likewise, Arg1 induction was significantly greater after infection with strain ME49, as compared to strain RH." (PMID 29459868, 2018). "Notably, let-7e inhibition regulated Arg1 and Nos2 expression during infection, corroborating the importance of the TLR signaling cascade in the mechanism regulating Arg1 and Nos2 expression at the transcriptional level." (PMID 30555476, 2018). "Accordingly, we found increased RNA abundance of Arg1, Socs1, Sra1, Saa1, Ciita, Marco, Mgl2, Cd209d, Cd209e, Cd209f, Ccl1, Ccl11, Ccl17, Ccl19, Ccl20, Ccl22, and Ccl24 genes in Stat2−/− mice when compared to WT mice during super-infection." (PMID 30337919, 2018). "We then inhibited both IFNγ and Arg1 simultaneously during super-infection in WT and Stat2−/− mice." (PMID 30337919, 2018). "Moreover, naive BN showed a Th2 bias following infection with vMC0, as shown by an influx of alternatively activated macrophages (MGL1/ARG1) with parallel upregulation of Th2-associated cytokines (IL25/IL33)." (PMID 30150981, 2018). "Four weeks post-infection, a real-time PCR analysis of inflammatory gene expression revealed that purified macrophages from infected WT mice exhibited enhanced IL-10, Arg-1, MCP-1, RELMa, and IL-6 but reduced TNF-α, IL-12, and iNOS mRNA levels, which exhibited an M2 dominant- polarized phenotype." (PMID 30589840, 2018). "However, the levels of IL-6, MCP-1 (CCL2), IL-10, and Arg-1 mRNA were found to be downregulated at 6 weeks post-infection." (PMID 30589840, 2018). "After triggering specific M1 or M2 polarization, we observed that both ISG15+/+ and ISG15-/- BMDM presented the same levels of inducible nitric oxide synthase (iNOS) (M1 marker) and arginase-1 (Arg-1; M2 marker) protein by western blotting, independently of infection and of the presence of ISG15." (PMID 29077752, 2017). "This potentially could be detrimental during mycobacterial disease, where anti-mycobacterial T cells might be suppressed by Arg1+ myeloid cells, resulting in a blunted host response to infection." (PMID 29201027, 2017). "Recognition by TLRs induced antiparasitic activity and the production of pro-inflammatory cytokines, such as IL-1, IL-6, TNF, IL-12 e IFN-γ, which also could influence the rate of NOS2/ARG1 during infection." (PMID 29379478, 2017). "An increase of Il4, Arg1 and Ifng mRNAs in the spleen was observed in the R12 group, suggesting the existence of peripheral systemic mixed Th1/Th2 active immune responses in secondary infection." (PMID 28362822, 2017). "Interestingly, the expression of Arg1 during La-arg− infection was similar to the one observed during La-WT infection." (PMID 28276497, 2017). "Interestingly, while JMJD3 was found to negatively regulate few of the mycobacteria-responsive M1 markers of macrophages viz., Il12, Il1b and Cxcl2, the expression of M2 markers like Arg1, Mrc1, Il10, Tgfb, Ccl17 and Ccl2 on infection were JMJD3-dependent." (PMID 27532872, 2016). "Likewise, M. tuberculosis infection can induce Arg1 expression in murine macrophages, and specific elimination of Arg1 in macrophages decreased lung bacterial loads during in vivo infection." (PMID 27849167, 2016).